CD163 (CD163 molecule)
Diseases named in the same sentence as CD163 in open-access papers (continued):
Sharing a sentence is not in itself a finding about the gene and the disease.
tumor (continued). "Further analysis suggested that combination of N status with serum IL-8, IL-8(T) or CD163(IF) may be a new criterion for discriminating between OSCC patients at high and low risk for tumor relapse." (PMID 25461761, 2014). "The expressions of CD68 and CD163 were significantly associated with lymph node status, and SOX2 was significantly correlated with pathological grade and lymph node status, whereas ALDH1 was correlated with tumor stage." (PMID 24883329, 2014). "Recently, tumor-associated macrophages (TAMs) in lesional tissues have been shown to be a strong prognostic indicator of cHL by gene expression profile analysis and subsequent immunohistochemical detection using CD68 and CD163 as markers." (PMID 24489836, 2014). "The findings from the present study indicate that a patient’s serum IL-8 level may reflect his or her tumor microenvironment, which shows the expression of IL-8 in cancer cells and the infiltration of CD163-positive macrophages into the tumor invasive front." (PMID 25461761, 2014). "In addition, the results of the present multivariate analysis indicate that N status, IL-8 expression in the tumor and the infiltration of CD163-positive macrophages are independent factors which can affect and predict the clinical outcome of OSCC patients." (PMID 25461761, 2014). "Recently, in resected stage I-IIIA NSCLC patients we demonstrated densities of tumour-associated CD66+ neutrophils and CD163+ macrophages were correlated with adverse clinical prognostic factors as well as CRP and white blood cell (WBC) systemic inflammatory markers." (PMID 23945200, 2013). "However, the average density of CD163+ cells was 22.83-fold and 4.11-fold higher in tumor and peritumoral liver tissue, respectively, compared with that of CD68+ cells." (PMID 23555776, 2013). "In aggregate, these reports suggest that increased numbers of MMP-9+ cells around the tumor might be connected with CD163+ M2 macrophages and contribute to the poor prognosis of the tumor-bearing host." (PMID 23606867, 2013). "Furthermore, we analyzed the M1/M2 ratios based on TAMs staining with CD68+ HLA-DR+ or CD68+ CD163+ in two consecutive tumor sections from each patient." (PMID 24324582, 2013). "The different abundance and activity of CD163 + M2 macrophages in tumor environment could explain the contrasting results reported in literature on the role of FcγR polymorphisms in mCRC." (PMID 23316197, 2012). "We could observe a significant statistical correlation between the amount of NOS2+ and CD163+ macrophages (P<0.0001), demonstrating the parallel presence of macrophages with both M1 and M2 phenotypes at the tumor invasive front." (PMID 23077543, 2012). "These CD163+ immature myeloid derived cells could be myeloid derived suppressor cells which have been shown to enhance tumor progression by having an immunosuppressive effect on anti-tumor effectors." (PMID 22824040, 2012). "When analyzing the prognostic value of Ki-67 in LMS, the authors concluded that this marker alone could be used as a survival indicator in LMS patients, although combination of tumor size, mitotic index, and Bcl-2 and CD163 expression worked even better." (PMID 22910809, 2012). "Furthermore, an increased infiltration of both NOS2+ and CD163+ macrophages at the tumor front was correlated to a significantly improved prognosis." (PMID 23077543, 2012). "It has to be said that there are a number of reports suggesting that also tumor cells and monocytes might express CD163, the detection of which depends on the antibody that is used." (PMID 22176642, 2011). "In addition, the results reveal that the densities of infiltrating CD163+ cells increase with the pathological grade of the tumor." (PMID 24213108, 2011). "Moreover, CD68/CD163 ratio was also increased in IDC-DCIS tumours (p=0.0004)." (PMID 41018083, 2025). "Targeting CD163 may thus attenuate tumor-induced immunosuppression." (PMID 40948759, 2025).
tumor (continued). "Within the tumor microenvironment, M2 cytokines, including IL-4, IL-13, and IL-10, are present, and TAMs in various cancer models exhibit an M2 activation profile characterized by increased expression of CD163, MRC-1, C-type lectins, IL-10, and Arg-1, as well as reduced production of IL-12." (PMID 40544275, 2025). "Moreover, the CD68/CD163 ratio was significantly lower in the TC group demonstrating the prevalence of anti-inflammatory M2-macrophages producing a wide range of angiogenic and tumor-promoting growth factors, cytokines and chemokines." (PMID 39936166, 2025). "CD163+ TAMs contribute to the overall immunosuppressive tumor microenvironment by interacting with other immune cells, such as T-cells and DCs, further suppressing the anti-tumor immune response and promoting a microenvironment favorable for cancer cell survival and progression." (PMID 40297579, 2025). "Several CAF IHC biomarkers, particularly CD163, MMP-9, periostin, and vimentin, significantly associated with prognosis in CRC, could be proposed as surrogates for the phenotypical characterization of the tumor microenvironment." (PMID 41450913, 2025). "Moreover, tumor-associated macrophages (TAMs) exhibit functional plasticity, polarizing toward either a pro-inflammatory, antitumor phenotype (M1, CD68-positive) or an anti-inflammatory, tumor-promoting phenotype (M2, CD163-positive)." (PMID 41239536, 2025). "The observed differential expression of IBA1 and CD163 may indicate that microglia and myeloid macrophages have different functions within the tumor microenvironment, or it could suggest that other factors are influencing their distribution and relative abundance." (PMID 40191733, 2025). "Tumor exosomes are involved in the omental metastatic colonization of GC by inducing adaptive responses in the TME, and they may be the main cause of the elevated expression levels of CD163." (PMID 41142606, 2025). "In addition, CD163+ cells may play a role in regulating angiogenesis and inflammation within the tumor microenvironment." (PMID 40361384, 2025). "Therefore, when considering the notably low (IL‐6 and IL‐27) and high (IL‐10) level of cytokines, as well as lower number of CD163+ cells, 2‐ME may also have rendered an anti‐tumor effects such as the greater tumor necrosis." (PMID 38600057, 2024). "Moreover, CD163, TNFAIP2, and SAMSN1 displayed a robust association with survival outcomes that remained significant independently of key clinical parameters such as gender, age at diagnosis, tumor content (%), and disease stage." (PMID 39015503, 2024). "The association between SFA skewness in the peri-tumoural region and the CD163 antibody on tumour-associated macrophages suggests that SFA export might not only alleviate cell apoptosis but further support pro-inflammatory activities." (PMID 38409583, 2024). "In addition, the mRNA level of CD163 and ARG1 (the markers of tumor-associated macrophage) was dramatically decreased in TDM and BMDM after B. thetaiotaomicron mixture, B. thetaiotaomicron culture medium, and acetic acid treatment, but not heat killed B. thetaiotaomicron or control bacteria E.coli." (PMID 38270111, 2024). "Finally, anti-tumor effects were evaluated by observing the appearance of M1 macrophages that might have infiltrated the tumor tissue from staining images with F4/80 and CD163 antibodies." (PMID 39408898, 2024). "In contrast, focal immune niches had higher levels of CD163, and tendency (p = 0.10) towards higher level of CD66b, suggesting a higher proportion of immune suppressive myeloid cells (M2 macrophages and possibly neutrophils) located in tumor-adjacent focal clusters." (PMID 39026018, 2024). "Interestingly, in gastric cancers, the spatial locations of CD163 and CD206 TAMs were related to their proximity to tumor cells and associated with specific environmental gene signatures and PD-L1 expression, implying an interactive process between cancer cells and the TME." (PMID 38893266, 2024).
tumor (continued). "In this study, we found a significant relationship between tumoral and stromal LLT1 expression and the presence of tumor-infiltrating CD163+ M2 macrophages (i.e., protumoral and immunosuppressive phenotype), suggesting that LLT1 might have an immunosuppressive role in OSCC." (PMID 38673902, 2024). "However, there were fewer CD163+ cells and greater tumor necrosis in 2‐ME treated mice." (PMID 38600057, 2024). "Some studies indicate that it could be used to identify M1 macrophages that oppose tumor growth, but others suggest that, along with CD163, it can be used as a marker of M2 polarization since its higher expression is associated with decreased survival in GB patients." (PMID 39796053, 2024). "When they shift towards the CD163 + 204 + M2-TAM phenotype through the activation of the signal transducer activator (STAT3) pathway caused by an immunosuppressive cytokine loop, they promote immunosuppression, drug resistance, tumor progression, and metastasis." (PMID 39061137, 2024). "The co-clustering of monocytes co-cultured with PDAC tumor cells or fibroblasts, indicates that fibroblasts can also differentiate monocytes to macrophages with a TAM phenotype, characterized by expression of CD163 and CD206, markers known to be associated to pro-tumoral immunosuppressive TAMs63,64." (PMID 38594506, 2024). "Additionally, the most frequent cell population, which was hematopoietic lin−HLA-DR+ cells, expressed CD11c, CD33, CD141, and CD163, which could indicate that it was a tumor-infiltrating macrophage population." (PMID 37894472, 2023). "In the present study we clearly demonstrated an elevated number of macrophages in the tumor environment in comparison with normal salivary gland tissue but even more interesting is the finding of the almost complete polarization of macrophages in CD163-positive–M2-macrophages." (PMID 36856809, 2023). "In particular, M1 macrophages are regarded as anti-tumor and typically identified by the surface markers CD86 and CD64, while M2 are polarized macrophages, commonly considered tumor-associated macrophages (TAMs) and typically express the surface markers CD206 and CD163." (PMID 37033265, 2023). "‐Depletion of CD163+ Tim4+ macrophages by diphtheria toxin‐mediated specific ablation prevented metastatic spread and invasive disease.‐Depletion of CD163+ macrophages by CD163‐targeted, doxorubicin‐loaded, lipid nanoparticles, delayed omental tumor progression." (PMID 36658699, 2023). "Hence, CD68+ and CD163+ TAM might collaborate in assisting tumoral cells to leave the primary tumor and invade lymph nodes due to the increasing vascularization and the induction of tumoral cell spreading." (PMID 37465638, 2023). "Similarly to patient#2, CD64+CD68-CD163- and CD64+CD68+CD163- TAM were found in the tumor nest." (PMID 37691949, 2023). "Moreover, in some cases there is CD163 staining in the cytoplasm and membrane of tumour cells." (PMID 36928373, 2023). "Finally, it is crucial to unravel whether IL4I1 derived from MHCII+ CD163− TAMs initiates the tumor control or is merely a consequence of the tumor regression to develop an accurate therapy targeting this enzyme." (PMID 37526660, 2023). "In addition, fewer CD163 + M2 macrophages were detected in post-infusion tumor specimens." (PMID 36617554, 2023). "Interestingly, in phase II clinical trial on ESCC patients, a low dose of metformin does not increase the total number of F4/80+ macrophage populations; however, it decreases tumor-promoting CD163+ macrophages and increases tumor-suppressive CD11c+ macrophages." (PMID 37686159, 2023). "Moreover, there is positive CD163 staining in the cytoplasm and membrane of tumour cells." (PMID 36928373, 2023).
tumor (continued). "Three categories of quantitative IHC image features (CD8, CD163, PD-L1) were extracted from the registered WSIs for subsequent evaluation of expression and distribution within different cellular components/regions (stroma, tumor, lymph) including an overall evaluation of all tissue components." (PMID 35892487, 2022). "Thus, in the near future, multiple diagnostic assessments measuring or quantifying HIF-1α, CAIX, mTor or CD68/CD163 balance in tumor specimens and/or plasmatic samples might be proposed during the OTS patient journey to evaluate outcome risks." (PMID 35326631, 2022). "Characterization of the Tumor Immune Microenvironment (TIME) involved the immunohistochemical analysis of PD-L1, and number and distribution of CD3+, CD4+, CD8+ Tumor Infiltrating Lymphocytes (TILs) and CD163+ Tumor Associated Macrophages (TAMs), focusing on immune-vascular localization." (PMID 35805021, 2022). "However, an abnormal increase in the level of CD163+ cell infiltration was observed in HPD tumours." (PMID 36104359, 2022). "Moreover, a higher percentage of tumor cells, intra-tumoral CD163+ macrophages and Treg cells within a 20 μm radius from CTL was associated with a longer DFS only in females, as well as a higher amount of interactions between PD-L1+ macrophages and PD-1+ T cells." (PMID 36123711, 2022). "In addition, we observed a negative correlation of HLA-DR expression with that of CD163 in our cell culture model, which is in close agreement with the literature of tumor-associated macrophages." (PMID 36359389, 2022). "Importantly, this “reprogramming” of macrophages mediated the pro-tumor response to pancreatic sympathectomy, as selective depletion of the CD163+ TAM population—which represents only a small proportion of all TAMs—was sufficient to rescue the overall survival of sympathectomized KIC mice." (PMID 35418199, 2022). "Thus, the effect of TYMP and CD163 gene expression on CRC carcinogenesis may vary depending on whether these genes are mostly expressed in tumor epithelial or stromal cells." (PMID 35567733, 2022). "However, whether the elevated MDSCs and CD68+CD163+M2-like macrophages promote tumor metastasis still needs a longer follow-up visit in NSCLC patients during radiotherapy and also deserves further investigations." (PMID 35928634, 2022). "Our study additionally proposes a possible role for tumors to attract FoxP3+, as well as CD163+ cells, that may afterwards participate in suppression pathways, resulting in the impairment of endogenous antitumor immune responses within the tumor microenvironment." (PMID 36551693, 2022). "According to the ratio of anti-inflammatory (CD163+) to pro-inflammatory TAMs, a significant skew towards the pro-inflammatory phenotype was observed in the nsECT2-treated group and tendentiously decreased in nsECT3 and nsECT4-treated mice, compared to untreated tumour-bearing mice." (PMID 36551739, 2022). "Thus, density numbers of infiltrating CD8+, CD4+, and FOXP3+ T-cell lymphocytes, CD20+ T-cell lymphocytes, and CD68+ and CD163+ macrophages were separately evaluated in both the tumor nests and surrounding stroma, and the mean numbers were correlated with the mean values for NLR, PLR, SII and LMR." (PMID 35958590, 2022). "Thus, sympathetic axon sprouting in PDAC and its precursor lesions may result in a local increase in the release of norepinephrine, which can directly influence pancreatic macrophages, reducing CD163 expression and the acquisition of a pro-tumor phenotype." (PMID 35418199, 2022). "Therefore, treatment-naïve primary tumor samples were stained with antibodies against CD163." (PMID 36058929, 2022). "Furthermore, Gal-9 is mainly expressed in CD68+CD163+ KCs, indicating it may promote tumor progression through the induction of immunosuppressive microenvironment." (PMID 35202002, 2022).
tumor (continued). "In addition, EBF1-expressing cells did not express monocyte/macrophage markers CD68, CD163 or Tie-2, recognized markers of tumor-associated macrophages with pro-angiogenic properties." (PMID 34272603, 2021). "Also, tumor‐associated macrophages (TAM) expressing CD163 were related to vascular invasion, nonluminal subtypes, and interval breast cancer." (PMID 34076969, 2021). "In this panel, PD-L1 (immune checkpoint), CD3 (T cells), CD8 (cytotoxic T cells), CD163 (histiocytes/macrophages), and FoxP3 (regulatory T cells) were analyzed in epithelial tumor (CK+) and surrounding stromal (CK-) compartments, respectively, across 3 different tumor types." (PMID 33596250, 2021). "Moreover, we found the expression of CD163 was positively linked to the AJCC tumor stage (r = 0.326, P = 0.003, data not shown)." (PMID 34131104, 2021). "Given that aminobisphosphonate has been reported to decrease pro-MMP-9 and may abrogate the induction of CD163+ M2 macrophages in the tumor microenvironment, bisphosphonates might be effective for the prevention of not only bone metastasis but also disease progression in patients with invasive EMPD." (PMID 34436026, 2021). "Interestingly, CD163 gene expression was also significantly increased upon tumor recurrence in GBM." (PMID 34572134, 2021). "Interestingly, this increase does not appear to be linked to CD163 expression, as CD163 expression appears to not change or decrease upon tumor recurrence." (PMID 34572134, 2021). "Given recent reports that the balance between effector and suppressor immune subsets may offer more useful prognostic information, we evaluated the correlation between ratios of CD8+/FOXP3+, CD3+/FOXP3+, CD4+/FOXP3+, and CD68+/CD163+ and survival in tumor samples at diagnosis and after NACT." (PMID 32852603, 2021). "It was reported that CD163+ tumor-associated macrophages could inhibit T-cell proliferation and activation by secreting CCL22, IL-10, and TGF-β and recruiting regulatory T cells (Tregs) to tumor tissues." (PMID 35155189, 2021). "Likewise, expression of PDL1+ CD163+ in the tumor infiltrates indicative of M2 TAMs was accompanied by high numbers of Tregs both of which permeated into the metastatic LNs barricading the tumor cells leading to poor prognosis." (PMID 33996630, 2021). "Our working hypothesis is that the presence of tumor-infiltrating immune cells, here represented as macrophages characterized by the markers CD68, CD163, and CCL2, could be associated with a better prognosis, but that chemotherapy may not add an advantage for prognosis." (PMID 33467469, 2021). "After adjusting for tumor purity, the results showed that ATF3 expression was significantly correlated with macrophage subpopulations, including tumor-associated macrophages (TAMs; CCL2, r = 0.245, P = 4.16e−06), M1 (NOS2, r = 0.137, P = 0.08e−02), and M2 (CD163, r = 0.141, P = 8.90e−03)." (PMID 33407456, 2021). "Interestingly, a high number of CD3 + TILs is associated with high CD68 and CD163 expression in tumor nests, but not in the stroma, implicating a distinct colonization mechanism for lymphocytes and macrophages in various tumor compartments." (PMID 34200100, 2021). "However, here we would like to know whether NFATc1 may have roles in activation of TAMs CD163+ in tumor microenvironment of HL." (PMID 34181355, 2021). "Finally, the GG genotype of TGFB1 rs6957 associated with lower tumor TGFβ levels (p = 0.03) and less CD163+ macrophages (p = 0.01), but did not modulate patients’ survival." (PMID 33648463, 2021).